CTSD (cathepsin D)
Diseases named in the same sentence as CTSD in open-access papers (continued):
Sharing a sentence is not in itself a finding about the gene and the disease.
Alzheimer disease (continued). "Levels of several lysosomal proteases including cathepsin D and cathepsin B are increased in CSF and post mortem brain tissue of Alzheimer’s disease patients." (PMID 35732154, 2022). "Mouse models of Alzheimer’s disease showed that Aβ aggregates increase astrocyte lysosome pH, resulting in a decreased cathepsin D activity and lysosome damage." (PMID 34198733, 2021). "The deamidation of glutamine (Q) in the peptide sequence (QDENP) has been shown to block its degradation by the protease cathepsin-D in Alzheimer's Disease." (PMID 31024521, 2019). "Expansion of the lysosomal system, including cathepsin D upregulation, is an early and prominent finding in Alzheimer's disease brain." (PMID 20664788, 2010). "As in Alzheimer's disease, microarray analysis of a well-characterized Drosophila model of tauopathy identified lysosomal dysfunction and cathepsin D upregulation." (PMID 20664788, 2010). "The connection between Alzheimer's disease and cathepsin D has also been made in multiple additional studies, including investigations of patient brain tissue, cerebrospinal fluid, fibroblasts, and genetic studies." (PMID 20664788, 2010). "Cathepsin D is upregulated with age in a Drosophila model of Alzheimer's disease and related tauopathies." (PMID 20664788, 2010). "Interestingly, oxidative stress, a well-described trigger of increased lysosomal permeability and implicated both in Alzheimer's disease and in our Drosophila tauopathy model, may be a potential contributor to the marked increase in tau toxicity observed in the cathepsin D null background." (PMID 20664788, 2010). "The early papers demonstrating lysosomal abnormalities in Alzheimer's disease brain demonstrated upregulation of cathepsin D mRNA and protein in dying neurons in the disease." (PMID 20664788, 2010). "Of the widespread lysosomal abnormalities described in Alzheimer's disease, there is conspicuous upregulation of mRNA and protein of the aspartyl protease cathepsin D within degenerating neurons." (PMID 20664788, 2010). "The human disease literature suggests that early lysosomal abnormalities, including cathepsin D upregulation, are particularly prominent in Alzheimer's disease compared to other adult-onset neurodegenerative disorders." (PMID 20664788, 2010). "The discovery that mutations in cathepsin D cause aggressive neurodegeneration in one form of neuronal ceroid lipofuscinosis, a childhood neurodegenerative lysososomal storage disease has suggested upregulation in Alzheimer's disease may be a compensatory protective response." (PMID 20664788, 2010). "Interestingly, several cathepsins, including CTSB, CTSD and CTSL have been implicated in the pathogenesis not only of PD, but also additional neurodegenerative disorders including Alzheimers Disease (AD)." (PMID 39587654, 2024). "In Alzheimer Disease (AD), possible biomarkers with diagnostic relevance have been identified, such as elevated lysosome-associated membrane protein 1 (LAMP1) and cathepsin D levels in plasma EVs, and low levels of EV-associated miRNA-193b in cerebrospinal fluid." (PMID 35879759, 2022). "In addition, it was shown that the levels of cathepsin D are similar among patients with mild and severe Alzheimer’s disease and mild cognitive impairment." (PMID 34198733, 2021). "However, high exosomal levels of cathepsin D and LAMP1 together with low levels of the 70 kDa heat shock proteins were detected in the blood of patients with Alzheimer’s disease, suggesting a diagnostic role for this protease." (PMID 34198733, 2021). "Interestingly, the QTL cluster at Lca371 underlying growth traits of Asian seabass showed similarity to the cathepsin D gene of human, which is related to cancer and Alzheimer's disease and has become a hotspot of human genetics study." (PMID 21457569, 2011).
Alzheimer disease (continued). "Interestingly, a QTL cluster at Lca371 underlying growth traits of Asian seabass showed similarity to the cathepsin D gene of human, which is related to cancer and Alzheimer's disease." (PMID 21457569, 2011). "We therefore determined whether cathepsin D downregulation could influence tau-induced neurotoxicity in an animal model of Alzheimer's disease and related tauopathies." (PMID 20664788, 2010). "Additionally, CTSD plays a crucial role in neurodegenerative diseases, and alterations in its expression may contribute to Parkinson’s disease, Alzheimer’s disease, and Huntington’s disease." (PMID 40969353, 2025). "Our group recently discovered that the lysosomal aspartyl protease, cathepsin D (CatD) is, by several measures, the principal protease responsible for degrading intracellular pools of the amyloid β-protein (Aβ), which accumulates abnormally in Alzheimer disease (AD)." (PMID 37047718, 2023). "This endogenous inhibitor does not target all lysosomal proteases, implicated in Alzheimer’s disease, it does not impact the activity of Cathepsin D, which has recently been suggested to have a role in disease development via its function in amyloid-β and tau clearance." (PMID 37580797, 2023). "Hence, it is not surprising that genetic variants within the CTSD gene have been linked to neurodegenerative diseases, like Parkinson’s and Alzheimer’s disease (PD, AD), as well as the lysosomal storage disorder neuronal ceroid lipofuscinosis type-10 (NCL10)." (PMID 33681191, 2021). "Tau phosphorylation is a well-described post-translational modification in tauopathies, including Alzheimer's disease, and plays a critical role in mediating tau neurotoxicity in Drosophila, but there was no change in tau phosphoepitope levels to explain the modulatory effect of cathepsin D." (PMID 20664788, 2010). "Publications have indicated that this SNP may: modify the secretion or maturation of the cathepsin D profragment; lead to a reduction in cerebrospinal fluid (CSF) tau concentration in Alzheimer's disease; and show a decrease in general intelligence testing scores in a healthy older population." (PMID 18426579, 2008). "For this study we selected a SNP in the gene coding for the cathepsin D protein (CTSD), that had already been the subject of extensive publications in the field of Alzheimer's disease (AD) a neurodegenerative disease with some pathological similarities to CJD." (PMID 18426579, 2008). "Statistical analysis showed that cathepsin D level in plasma of patients with Alzheimer’s disease is decreased comparing to the subjects without cognitive impairment." (PMID 34198733, 2021). "This is consistent with some prior studies that have shown the presence of lysosomal proteins in isolated exosomes, including cathepsin D and LAMP-1 in exosomes from Alzheimer disease patients and glucocerebrosidase in exosomes from Parkinson’s disease patients." (PMID 30987321, 2019). "A number of genetic linkage studies have suggested a role for cathepsin D in the pathogenesis of Alzheimer's disease, although these results have not been replicated in all cohorts examined, including recent genome wide association studies." (PMID 20664788, 2010). "Further, generation of a C-terminally truncated form of tau found in Alzheimer's disease patients is significantly increased in the absence of cathepsin D. We show that truncated tau has markedly increased neurotoxicity, while solubility of truncated tau is decreased." (PMID 20664788, 2010).
neuronal ceroid lipofuscinosis (33 papers, 2010 to 2025). "While cathepsin D has been also associated with disorders such as neuronal ceroid lipofuscinosis, its intracellular roles remain poorly understood." (PMID 41181714, 2025). "CTSD has been implicated in multiple neurodegenerative diseases, including a fatal congenital form of neuronal ceroid lipofuscinosis caused by CTSD mutations." (PMID 37131250, 2023). "Genes for lysosomal proteases are increased, including CTSB, CTSC and CTSD, which is mutated in neuronal ceroid lipofuscinosis (NCL) type 10." (PMID 37747131, 2023). "It is noteworthy that the Cathepsin D (ctsd) gene is mutated in human neuronal ceroid lipofuscinosis." (PMID 38201257, 2023). "CLN10 disease, an early infantile neuronal ceroid lipofuscinosis, is associated with a gene that encodes cathepsin D (CtsD), one of the major lysosomal proteases." (PMID 35804072, 2022). "The down-regulation of human cathepsin D is associated with neurodegenerative disorders, such as neuronal ceroid lipofuscinosis." (PMID 34198733, 2021). "Biallelic ASAH1, SLC17A5, and CTSD mutations cause Farber lipogranulomatosis, Salla disease and neuronal ceroid lipofuscinosis (CLN10), respectively." (PMID 34149605, 2021). "Intriguingly, mutations resulting in the inactivation or mislocalization of Cathepsin D lead to neuronal ceroid lipofuscinosis, suggesting a convergent pathogenic mechanism with other LSDs." (PMID 34909687, 2021). "They include ASAH1 (acid ceramidase, causing Farber disease), CLN10 (cathepsin-D, a lysosomal aspartyl proteinase causing neuronal ceroid lipofuscinosis), and SLC17A5 (sialin, causing Salla disease)." (PMID 31284408, 2019). "A direct and critical role for cathepsin D in the metabolism of lipofuscins comes from cathepsin D-deficient mice, which showed increased deposition of one type of neuronal ceroid lipofuscinosis." (PMID 27257626, 2016). "In a cathepsin D‐/‐ model of neuronal ceroid‐lipofuscinosis, similar synaptic loss was observed in the VPL/VPM, but pathology was similarly limited in the relevant somatosensory cortex." (PMID 25727649, 2015). "CTSD is the gene encoding Cathepsin D (CTSD), a lysosomal protein hydrolase, and homozygous CTSD deficiency results in neuronal ceroid-lipofuscinosis, which is characterized by the early onset, progressive neurodegeneration." (PMID 26448324, 2015). "Cathepsin D homozygous inactivation in humans causes congenital neuronal ceroid lipofuscinosis (NCL) with postnatal respiratory insufficiency, status epilepticus, and death within hours to weeks after birth." (PMID 20388210, 2010). "In human patients with neuronal ceroid lipofuscinosis (NCL) due to a Cathepsin D deficiency, the brains were extremely atrophic with massive neuronal loss throughout the cortex, accompanied with intense α-synuclein staining." (PMID 20388210, 2010). "Loss of cathepsin D results in an aggressive form of the lysosomal storage disease neuronal ceroid lipofuscinosis in human patients." (PMID 20664788, 2010). "The complete loss of cathepsin D in patients results in a devastating form of the lysosomal neurodegenerative disorder, neuronal ceroid lipofuscinosis." (PMID 20664788, 2010). "In humans, several pathogenic mutations in the gene encoding CtsD are linked to the congenital, late infantile or juvenile onset of type 10 Neuronal Ceroid Lipofuscinosis (NCL), a severe neurodegenerative LSD characterised by the accumulation of autofluorescent lipopigments." (PMID 39851495, 2025). "CTSD gene homozygous inactivation was reported to cause human congenital neuronal ceroid lipofuscinosis (NCL) with postnatal respiratory insufficiency, epilepsy, and death within hours to weeks after birth, due to neurological defects and absence of neuronal α-synuclein accumulation." (PMID 34198733, 2021). "Furthermore, CTSD gene knockout or mutations also lead to neuronal ceroid lipofuscinosis, which is characterised by lipopigments and proteins accumulating in lysosomes." (PMID 31690989, 2020).
neuronal ceroid lipofuscinosis (continued). "However, it is known that loss or mutation of another lysosomal protease, CtsD can lead to congenital neuronal ceroid-lipofuscinosis characterised by accumulation of lipofuscin laden vacuoles and oxidative damage to brain pericytes and other cells." (PMID 30559339, 2018). "Second, loss of cathepsin D function in humans causes marked lysosomal proliferation, abnormal accumulation of lysosomal storage material and aggressive neurodegeneration in an infantile form of neuronal ceroid lipofuscinosis." (PMID 20664788, 2010). "For instance, neuronal ceroid lipofuscinosis (NCL) has been linked to mutations of genes related to lysosomal function, including GRN (granulin), CTSD (cathepsin D) and CLN5 (ceroid lipofuscinosis neuronal protein 5)." (PMID 41387918, 2025). "Mutations of the human gene encoding cathepsin D, CTSD, that severely impair enzyme activity gives rise to the lysosomal storage disorder neuronal ceroid lipofuscinosis." (PMID 33932147, 2021). "In particular, cathepsin D is involved in various diseases, including breast cancer metastasis, atherosclerosis, Alzheimer’s disease and neuronal ceroid lipofuscinosis (NCL)." (PMID 31547147, 2019). "We further suggest a similar relationship in mammalian systems because we show activated caspase and formation of caspase-cleaved tau in cathepsin D null mice and sheep, both well-established models of neuronal ceroid lipofuscinosis." (PMID 20664788, 2010). "In addition to cathepsin D, several cathepsins are associated with inflammatory neurological diseases including Niemann–Pick type C (NPC) disease, neuronal ceroid lipofuscinosis (NCL) and Alzheimer’s." (PMID 32668602, 2020). "CtsD gene knockout mice die at approximately postnatal day 26, exhibiting a small amount of intestinal necrosis, and a neuropathologic defect that resembles the phenotype of neuronal ceroid-lipofuscinosis (known as CLN10)." (PMID 30959855, 2019). "Human patients who lack functional Cathepsin D whether by protein truncation, misfolding, or depletion results in congenital neuronal ceroid-lipofuscinosis (NCL), a disease that results in rapid neurodegeneration and death within hours to weeks after birth." (PMID 27114848, 2016). "Interestingly, so far out of ~10 genes known that cause lysosomal storage disease neuronal ceroid lipofuscinosis (NCL), only tripeptidyl peptidase I and Cathepsin D are proteases." (PMID 20388210, 2010). "Furthermore, GRN mutant cells were associated with abnormal lysosomal functions and neuronal ceroid lipofuscinosis (NCL), characterized by reduced proteolysis and decreased expression of cathepsin D in cortical neurons." (PMID 41155255, 2025).
Parkinson disease (23 papers, 2010 to 2025). A progressive degenerative disorder of the central nervous system characterized by loss of dopamine producing neurons in the substantia nigra and the presence of Lewy bodies in the substantia nigra and locus coeruleus. "Univariate MR analysis results indicated a correlation between higher levels of Cathepsin B (IVW (OR): 0.89, 95% (CI): 0.83, 0.95, p = 0.001) and Cathepsin D (OR: 0.80, 95%CI: 0.68, 0.95, p = 0.012) with a decreased risk of Parkinson’s disease." (PMID 39420987, 2024). "The study also found a causal relationship between Cathepsin D and Parkinson’s disease, as well as between Cathepsin E and both stroke and multiple sclerosis, and between Cathepsin O and stroke." (PMID 39420987, 2024). "Levels of Cathepsin D protein and total-beta hexosaminidase activity were significantly higher in Gaucher disease and Parkinson’s disease with GBA mutations than controls." (PMID 24574503, 2014). "The study conducted in an ATP13A2 deficient zebrafish (Parkinson’s disease model) confirmed the reduced cathepsin D expression and showed lysosomal abnormalities, leading to the degeneration of dopaminergic neurons arguably caused by intracellular trafficking impairment." (PMID 34198733, 2021). "Plasma levels of CTSD (Cathepsin D) have been suggested as a biomarker for IR as they correlate with IR, and are associated with insulin sensitivity and hepatic inflammation, and have also been reported as a potential diagnostic biomarker for AD and Parkinson's disease." (PMID 37891690, 2023). "Application of recombinant CLN10/CTSD (Cathepsin D) ameliorates ⍺‐synuclein aggregation and Parkinson disease pathology in ⍺‐synuclein A53T variant‐containing induced Pluripotent Stem Cells (iPSC)‐derived neurons." (PMID 39822020, 2025). "Cathepsin D participates in prosaposin cleavage too, and, together with progranulin, participates in a lysosomal network involved in Parkinson’s." (PMID 38607042, 2024). "Conversely, some studies showed increased levels of cathepsin D in Parkinson’s fibroblasts and dopaminergic neurons." (PMID 34198733, 2021). "Sulfated glycosaminoglycans, which hoard in substantia nigra of Parkinson’s disease patients along with α-synuclein, decrease the activity of cathepsin D." (PMID 34198733, 2021). "Decreased levels of cathepsin D were also detected in plasma of patients with Parkinson’s disease comparing to the patients with essential tremor." (PMID 34198733, 2021). "The unique role of cathepsin D in α-synuclein proteolysis, which accumulates in Parkinson’s disease, has been proven." (PMID 34198733, 2021). "Other experiments also established decreased cathepsin D activity in substantia nigra and frontal cortex of patients with Parkinson’s disease and Lewy body dementia." (PMID 34198733, 2021). "CTSD, together with calcineurin, have been shown to protect against alpha-synuclein toxicity in a yeast model of Parkinson’s disease." (PMID 33572113, 2021). "On western blotting, cathepsin D was significantly increased in Gaucher disease [median 50% increase (IQR 32–100%), Mann-Whitney U-test P < 0.0001] and Parkinson’s disease with GBA mutation [median 30% increase (IQR 20–40%), P = 0.002] fibroblasts." (PMID 24574503, 2014). "In this context it is interesting that some patients with NCL have parkinsonism and that brains of NCL patients caused by Cathepsin D deficiency (CLN10) show intense alpha-synuclein staining." (PMID 23814539, 2013). "Using chronic 1-methyl-4phenyl-1,2,3,6-tetrahydropyridine treatment of rhesus monkeys to model Parkinson's disease, we found a upregulation of Cathepsin D, a lysosomal aspartic protease, in the caudate nucleus of treated monkeys." (PMID 21777416, 2011). "In addition, neurosin, the MMP family, cathepsin D and plasmin also showed fibrinolytic activity against alpha-synuclein in Parkinson's disease." (PMID 40302732, 2025).